MIR761 (microRNA 761)
Synonyms: hsa-mir-761
Gene: MicroRNA gene on chromosome 1 (51,836,344 to 51,836,402, reverse strand). Ensembl gene ENSG00000283899.
Gene Ontology:
Biological process: miRNA-mediated post-transcriptional gene silencing
Cellular component: RISC complex
Homologues: Orthologues: chimpanzee MIR761 (100% identical), dog MIR761 (100% identical), guinea pig MIR761 (100% identical), macaque mml-mir-761 (100% identical), pig MIR761 (100% identical), rabbit MIR761 (100% identical), rat Mir761 (100% identical), mouse Mir761 (98% identical).
Diseases named in the same sentence as MIR761 in open-access papers:
MIR761 is named in the same sentence as 2 diseases in open-access papers, as found by Europe PMC text mining. Sharing a sentence is not in itself a finding about the gene and the disease. The quoted sentences say what the papers report.
cancer (1 paper, 2025). A tumor composed of atypical neoplastic, often pleomorphic cells that invade other tissues. "The first was a group of novel genes and the second was a group of genes associated with various cancer and tumour diseases (TXNDC12, NRDC, MIR761, ITSN2, NCOA1, SCUBE2, DENND5A, RCN2)." (PMID 40003092, 2025).
MIR761 also shares sentences with these, for which no sentence is quoted: tumour diseases (1 paper).